ABCG2 (ATP binding cassette subfamily G member 2 (JR blood group))
Diseases named in the same sentence as ABCG2 in open-access papers (continued):
Sharing a sentence is not in itself a finding about the gene and the disease.
gout (continued). "However, genome‐wide association studies provided the first evidence for a physiological role of ABCG2 when the most frequent ABCG2 polymorphism (C421A or rs2231142, leading to a Q141K replacement) turned out to be the most strongly predictive allele for hyperuricemia/gout." (PMID 32978801, 2020). "Given this, along with evidence that ABCG2 rs2231142 has a stronger effect on urate and gout in males than females, male-only analyses were also done, which yielded similar results." (PMID 32164793, 2020). "When the ABCG2 locus was included in the analysis, all of these subtypes except for normal type gout then showed significant enrichment of selection pressure." (PMID 32238385, 2020). "The main advantage of our study was primarily its detailed genetic analysis of urate transporters GLUT9, URAT1, and the previously analyzed ABCG2 in a clinically and biochemically characterized cohorts of Czech patients with primary hyperuricemia and gout." (PMID 32759716, 2020). "This emphasizes the strong influence of ABCG2 and SLC2A9 variants on gout development and points out the importance of identifying high risk patients having these genetic variants." (PMID 33087043, 2020). "There is growing evidence that the reduced level and/or function of ABCG2 contribute to the development of the painful disease, gout." (PMID 31254042, 2020). "Major transporters involved in renal urate disposition that are encoded by gout-risk genes include SLC22A12 (encoding URAT1), SLC2A9 (encoding Glut9), and the urate secretory transporter ABCG2 (ATP-binding cassette)." (PMID 33330529, 2020). "As expected, analysis including ALDH2 and outside of ABCG2 showed significant enrichment of selection pressure except for normal type gout." (PMID 32238385, 2020). "The results revealed that the Japanese population has evolved to have higher SUA levels, which can result in gout, due to the ABCG2 locus in addition to the already-known ALDH2 gene." (PMID 32238385, 2020). "Replication studies showed conflicting effects of ABCG2 and SLC2A9 polymorphisms on gout and serum urate." (PMID 33087043, 2020). "From ROL type gout, rs4148155 of ABCG2 (pmeta=9.75×10–46; OR=2.79) and rs11066008 of ACAD10 (ALDH2) (pmeta=4.20×10–12; OR=1.79) were revealed to have an association." (PMID 32238385, 2020). "In this study, we analyzed the ABCG2 gene in a hyperuricemia and gout cohort focusing on patients with pediatric-onset, i.e., before 18 years of age." (PMID 30894219, 2019). "Currently, the biological mechanism on how ABCG2 interacts with PKD2/NAP1L5 in the pathogen of gout is unclear." (PMID 30899057, 2019). "ABCG2 SNP rs2231142 and the gout comorbidities including nephrolithiasis and CKD were associated (P = 0.014 and P = 0.026)." (PMID 31367212, 2019). "Further investigation should be implemented to obtain more information on the association of ABCG2 and SLC22A12 SNPs or other different genetic variants with gout." (PMID 30621105, 2019). "Genome-wide association studies (GWASs) have explored many genes associated with gout, for instance, ABCG2, PKD2, SLC2A9, KCNQ1, SLC22A12 and SLC17A1 for gout disease among individuals of European descent." (PMID 30899057, 2019). "In people of European ancestry, gene-sex interactions for gout risk exist for ABCG2 and PDZK1, with the effect alleles exerting a greater influence on gout risk in men than in women." (PMID 30626429, 2019). "In a large population of European ancestry, ABCG2 and PDZK1 gene-sex interactions exist for gout risk, with the serum urate-raising alleles exerting a greater influence on gout risk in men than in women." (PMID 30626429, 2019). "In spite of these restrictions, our study was the first to reveal associations between SNPs (rs72552713 in ABCG2, and rs11231825 in SLC22A12) and gout among Vietnamese." (PMID 30621105, 2019). "The role of lymphocytes related to gout development has been well recognized, but it unclear how ABCG2 interact with PKD2 in the inflammation stage of gout." (PMID 30899057, 2019).
gout (continued). "Screens for small molecule treatments have been instigated, including for Tangier disease (ABCA1), gout (ABCG2), Stargardt eye disease (ABCA4), progressive familial intrahepatic cholestasis type 2 (ABCB11), and congenital hyperinsulinemia." (PMID 30659068, 2019). "Our results show that genetic factors affecting ABCG2 function should be routinely considered in a hyperuricemia/gout diagnosis, especially in pediatric-onset patients." (PMID 30894219, 2019). "Our study aimed to assess the relationship between polymorphisms in ABCG2 and SLC22A12 and gout susceptibility in Vietnamese." (PMID 30621105, 2019). "In this large population of European ancestry, we have identified gene-sex interactions for ABCG2 (rs2231142) and PDZK1 (rs1471633) for gout risk, with the serum urate-associated SNPs exerting a greater influence on gout risk in men than in women." (PMID 30626429, 2019). "Coding regions of the ABCG2 gene were analyzed in 70 primary hyperuricemic, 182 gout patients, and 132 normouricemic individuals." (PMID 31739430, 2019). "In this study, we analyzed the ABCG2 gene in a Czech hyperuricemia and gout cohort focusing on pediatric-onset (before 18 years of age) patients." (PMID 30894219, 2019). "Of these, 13 variants were common (MAF ≥ 5%) and located in known serum urate GWAS loci, including rs2231142 (Q141K) in ABCG2 (beta: 0.22, p = 2.4 × 10−32; OR for gout: 2.05, p = 1.7 × 10−15), and other variants in SLC2A9, ABCG2, GCKR, SLC17A1, and SLC17A414." (PMID 30315176, 2018). "In the present study, we have examined the expression levels of the ABCG2 protein in healthy volunteers, gout patients, as well as age-matched clinical control subjects, and mapped the genetic background of the altered ABCG2 expression levels in DNA samples." (PMID 29749379, 2018). "Here, our study demonstrates that those with mutants in both ABCG2 and SLC2A9 genes cause an additive interaction effect for gout occurrence." (PMID 29453348, 2018). "Analysis of ABCG2 expression in the erythrocyte membranes of healthy volunteers and gout patients showed an enrichment of lower expression levels in the patients." (PMID 29749379, 2018). "SLC2A9 and ABCG2 are the two most prominent players in gout explaining ~5% of variance in serum urate levels." (PMID 30181573, 2018). "Further detailed clinical and molecular genetic studies are required to explore the effects of this mutation in gout, in ADME-tox properties of ABCG2 substrate drugs, e.g., statins, and in the treatment of drug resistant cancer cells (see46)." (PMID 29749379, 2018). "This study demonstrates that ABCG2 gene contributes to the development of not only hyperuricemia but also gout with solid evidence from the GWAS and endothelial cell model." (PMID 29453348, 2018). "We concluded that ABCG2 gene contributed to hyperuricemia but also gout, and that it was involved in the inflammation dysregulation via augmented IL-8 release in EC." (PMID 29453348, 2018). "Known genetic variants in SLC2A9 and ABCG2 were associated with urate and gout in a CKD cohort, with effect sizes for ABCG2 significantly greater in CKD compared to the general population." (PMID 30181573, 2018). "As documented, individuals with low level erythrocyte ABCG2 expression were found with an increased occurrence among the gout/hyperuricemic patients, as compared to the control individuals." (PMID 29749379, 2018). "After multiple correction, the association between two genes, ABCG2 and SLC17A4 (novel gout-associated gene), remained significant (OR = 1.56, PFDR = 3.68E-09; OR = 1.27, PFDR = 0.013, respectively)." (PMID 28252667, 2017). "And 11 of the significant variants were from the gout associated loci (GCKR, SLC2A9, ABCG2, CNIH2, MYL2-CUX2 (ALDH2) and BCAS3)." (PMID 28642574, 2017). "Variants in two genes, ABCG2 and SLC2A9, are consistently associated with hyperuricaemia and prevalent gout in many different populations." (PMID 28270222, 2017).
gout (continued). "Considering the important role of ABCG2 in gout, it is worth further investigating the molecular mechanism of NRBP1 in gout development." (PMID 28932319, 2017). "A genetic risk score including ABCG2, SLC2A9, SLC22A12, SLC22A11 and SLC17A3 has also shown interaction with alcohol intake for gout risk." (PMID 28566086, 2017). "Some of the previously reported gout associated loci (except ALDH16A1), including ABCG2, SLC2A9, GCKR, ALDH2 and CNIH2, were replicated." (PMID 28642574, 2017). "Six of the genes (A1CF, GCKR, ABCG2, TRIM46, SLC17A1 and HNF4G (novel gout-associated gene)) were still significantly associated with gout in males after multiple correction (all PFDR < 0.05)." (PMID 28252667, 2017). "Among the fourteen genes, six genes (ABCG2, SLC2A9, TRIM46, SLC17A1, A1CF and SLC17A4) affected both the elevation of the serum urate level and the development of gout from hyperuricemia and were identified as risk factors for gout." (PMID 28252667, 2017). "Our data identify novel ABCG2 structural domains and highlight essential residues within the structure that are amenable to therapeutic modulation in case of ABCG2-related diseases such as anticancer resistance or gout." (PMID 29061978, 2017). "The human ABC transporter ABCG2 (Breast Cancer Resistance Protein, BCRP) is implicated in anticancer resistance, in detoxification across barriers and linked to gout." (PMID 29061978, 2017). "The involvement of ABCG2 in pre-disposition to gout is familiar to many in the ABC transporter community, but here we heard about studies implicating two members of the ABCA subfamily in disease." (PMID 26517919, 2015). "We analyzed the relationship between ABCG2 transport dysfunction and gout and found that dysfunctional ABCG2 is responsible for approximately 78.4% of gout cases." (PMID 24857923, 2014). "The ATP-binding cassette (ABC) transporter, subfamily G, member 2 gene ABCG2/BCRP is located in a gout-susceptibility locus on chromosome 4q, which was previously identified in a genome-wide linkage study of gout." (PMID 24857923, 2014). "Recent GWAS of SUA identified several genes including GLUT9/SLC2A9 and ABCG2/BCRP, which have been revealed to have associations with urate disorders such as renal hypouricemia and gout." (PMID 24366390, 2014). "As described in this article, the SNPs of 421C>A and 376C>T in the human ABCG2 gene are recognized as clinical biomarkers to assess hyperuricemia and gout." (PMID 24287461, 2013). "An additional potential consequence of ABCG2 inhibition in patients with AML is impact on the risk of hyperuricemia and gout." (PMID 23967177, 2013). "In this review article, we provide an overview on the physiological role of human ABC transporter ABCG2 in purine metabolism and propose genotyping-based “personalized healthcare” to assess gout risk." (PMID 24287461, 2013). "Heterogeneity (allelic and genetic) is also evident in gene associations with gout between among South East Asian, Polynesian and European Caucasian at SLC2A9 and ABCG2." (PMID 24286387, 2013). "Since human efflux transporter BCRP/ABCG2 accepts uric acid as a substrate and genetic polymorphism causing a decrease of BCRP activity is known to be associated with hyperuricemia and gout, the contribution of rBcrp to intestinal secretion was examined." (PMID 22348008, 2012). "Genetic regulators of serum urate concentration that have been previously associated with gout at a genome-wide level of significance (P < 5 × 10-8) in Caucasian samples are SLC2A9 and ABCG2." (PMID 22541845, 2012). "Given the heterogeneity evident in risk conferred for gout at SLC2A9 and ABCG2 in the Asian and Austronesian populations studied so far, further investigation of these genes in samples derived from Asian and Austronesian people is warranted." (PMID 21658257, 2011). "We were able to confirm significant association between gout and SNPs in two established genes, namely SLC2A9 (rs734553 and rs6855911) and ABCG2 (rs2231142)." (PMID 19890391, 2009).
gout (continued). "Epigenetic modifications and post-translational modifications (PTMs) may contribute to the progression from HUA to gout by modulating the function of UA transporters such as ABCG2 and GLUT9 and involving the NLRP3/IL-β inflammatory axis." (PMID 42293766, 2026). "In addition to HLA-B*58:01, ongoing research is illuminating how common variants in genes encoding urate transporters – such as ABCG2, SLC2A9 (GLUT9), SLC22A12 (URAT1), and others – modulate serum urate levels and gout risk in different populations." (PMID 41329531, 2025). "Whole-genome sequencing studies further identify novel genetic loci (RCOR1, FSTL5-MIR4454) and transporter variants (ABCG2, SLC22A12) associated with early-onset gout, with RCOR1 promoting NLRP3 inflammasome activation and IL-1β release, which are key drivers of gouty inflammation." (PMID 40880930, 2025). "Additionally, curcumin notably increased the expression of urate transporter ABCG2 in the kidneys, suggesting its potential to ameliorate hyperuricemia and gout symptoms." (PMID 41035515, 2025). "In addition, many other genes, such as ABCG2, SLC22A11, and SLC17A1, also showed strong associations with gout, all surpassing the genome-wide significance threshold after the Bonferroni correction test (P = 0.05/19203 = 2.60 × 10−6)." (PMID 41075270, 2025). "While no other identified genes were currently linked to approved gout medications, the associated drugs targeting genes such as ABCG2, SLC22A11, and ADH1B—involved in metabolic and inflammatory pathways—may hold potential for repurposing in gout treatment." (PMID 41075270, 2025). "For example, FABIO highlighted GATA3 as important for asthma and ABCG2 for gout." (PMID 39621803, 2024). "Notably, FABIO prioritized multiple candidate genes previously validated for their association with the respective diseases, such as GATA3 for asthma; ABCG2 for gout; and SH2B3 for hypertension." (PMID 39621803, 2024). "It is not surprising that Patient 7 with this allelic variant had higher SUA and hyperuricemia but did not have gout because ABCG2 probably compensated for the efflux of urate." (PMID 38222853, 2024). "Problems with ABCG2 or genetic variations could worsen hyperuricemia by making it harder for the body to get rid of uric acid, leading to gout." (PMID 39598418, 2024). "None of the variants of the known gout and hyperuricemia-related genes were co-segregated with the disease phenotype in this family, including ABCG2, SLC2A9, SLC22A11, SLC22A12, SLC17A1, SLC17A3, PDZK1, and INHBB." (PMID 39433541, 2024). "Notably, the correlation of ABCG2 with gout (P = 5.39 × 10−8) and DXO with celiac disease (P = 1.40 × 10−7) displayed enhanced significance." (PMID 39009607, 2024). "Previous studies have found that the gut of gout patients is rich in the bacterial metabolites acetate, succinate, and glucose, which provide energy for the intestinal epithelium to excrete UA through the transporter ABCG2 and SLC2A9." (PMID 38674582, 2024). "Additionally, it impacts UA transporters like URAT1, GLUT9, ABCG2, as well as OATs and OCTs, thereby contributing to gout treatment." (PMID 38094893, 2023). "The human ABCG2 multidrug transporter plays a crucial role in the absorption and excretion of xeno- and endobiotics, contributes to cancer drug resistance and the development of gout." (PMID 37887994, 2023). "As expected, many transporter genes such as URAT1/SLC22A12, GLUT9/SLC2A9, ABCG2/BCRP, NPT1/SLC17A1, and OAT10/SLC22A13 were identified as having an association with gout and SU in addition to several enzyme genes, including the ALDH2 gene, which has a pivotal role in alcohol metabolism." (PMID 38137389, 2023). "Both ABCG2 and XDH inhibition have been associated with hyperuricemia and gout, providing further evidence of our hypothesis that these proteins act in the same pathway." (PMID 37218814, 2023).
gout (continued). "Additionally, it has been reported that single nucleotide polymorphisms (SNPs) of ABCG2 have an order of magnitude greater impact on the SUA and gout than do the SNPs of other urate transporters expressed in the intestine in the general population." (PMID 36639673, 2023). "We infer that the first choice in urate-lowering therapy for those with nephrolithiasis, the ABCG2 rs2231142 T allele, and gout should be xanthine oxidase inhibitors rather than an uricosuric agent." (PMID 36967798, 2023). "ABCG2 and SLC2A9 were also identified as mQTL of uric acid, the causative agent of gout." (PMID 36582826, 2023). "ABCG2 plays a critical role in the regulation of renal urate overload and extra-renal urate underexcretion, making it a potentially valuable target for pharmacological intervention in the management of hyperuricemia or gout." (PMID 38067624, 2023). "In addition, ABCG2 and PDZK1 gene-gender interactions are associated with gout risk in European populations." (PMID 35922835, 2022). "The genetics of hyperuricemia, which is universally accepted to be the cause of gout, involves genes such as SLC2A9 (encodes for GLUT9), SLC22A12 (encodes for URAT1), SLC22A13 (encodes for OAT4) and ABCG2; these are mostly involved in uric acid reabsorption and secretion." (PMID 35456363, 2022). "ABCG2, GCKR, MLXIPL, and cytochrome P450 family 1 subfamily A member 2 (CYP1A2) are variants associated with coffee consumption habits, and GCKR and ABCG2 are associated with low coffee intake and a high gout risk." (PMID 35813212, 2022). "The ABCG2, SLC22A12, and ALPK1 genes have been strongly associated with dysfunction of urate metabolism in patients with gout, but it is unknown how these transporters are expressed in patients with acute or chronic gout." (PMID 35505381, 2022). "The results revealed that the variants exhibited protective effects against developing gout, namely rs3733589 (SLC2A9), rs3775948 (SLC2A9), rs1014290 (SLC2A9), rs3109823 (ABCG2), rs2622604 (ABCG2), rs6532055 (ABCG2), rs72554040 (ABCG2), rs671 (ALDH2), rs78069066 (MAPKAPK5), and rs77768175 (HECTD4)." (PMID 36221101, 2022). "first proposed the correlation between the ABCG2 gene and uric acid level and gout." (PMID 35281005, 2022). "Patients with gout carrying an ABCG2 SNP (rs2231142) respond poorly to allopurine therapy." (PMID 35813212, 2022). "Interestingly, meta-analysis showed that ABCG2 SNP rs2231137 (p.V12M) was a protective factor for gout." (PMID 35922835, 2022). "Moreover, the association between ABCG2 rs2231142, HUA and gout risk varies with ethnicity, with an almost 3-fold increase of T-risk allele frequency in the East Asian population compared to the European population." (PMID 34531894, 2021). "Although a genetic analysis was not performed in this study, ABCG2 polymorphisms are likely to have affected the age of onset of gout." (PMID 34207250, 2021). "In this article, we aim to focus on ABCG2, which has been identified as an important urate transporter in the intestine and the kidney, and discuss its role in renal and extra-renal urate excretion as well as in primary hyperuricemia and early-onset gout." (PMID 34206432, 2021). "Also, multiple studies have reported that patients who carry ABCG2 rs2231142 are more likely to have gout, and hence, higher serum levels of uric acid." (PMID 34255797, 2021). "The A1CF variant still showed a significant association with gout in the presence of the dysfunctional variants of ABCG2 but was no longer significant without those variants, while the BAZ1B variant remained significant both with and without ABCG2 dysfunction." (PMID 33517564, 2021).